TGFBI (transforming growth factor beta induced)
Diseases named in the same sentence as TGFBI in open-access papers (continued):
Sharing a sentence is not in itself a finding about the gene and the disease.
prostate carcinoma (20 papers, 2008 to 2024). A carcinoma that arises from epithelial cells of the prostate gland. "For example, it was reported that the expression level of lncRNA H19 was significantly downregulated in the metastatic prostate cancer cell line and negatively correlated with the expression of the extracellular matrix protein TGFBI." (PMID 37552338, 2023). "DKK3 silencing reduced the level of extracellular matrix protein-1 (ECM-1) in prostate stromal cell-conditioned media but increased it in epithelial cell-conditioned media, and recombinant ECM-1 inhibited TGFBI-induced prostate cancer cell invasion." (PMID 29858602, 2018). "DKK3 silencing increased the level of the cell-adhesion regulator TGF-β–induced protein (TGFBI) in stromal and epithelial cell-conditioned media, and recombinant TGFBI increased prostate cancer cell invasion." (PMID 29858602, 2018). "Expression of TGFBI in prostate cancer is repressed by promoter methylation and by miR-675, which inhibits prostate cancer migration." (PMID 29858602, 2018). "In summary, in the contexts of prostate epithelial cell acinar morphogenesis and prostate cancer cell invasion, TGFBI and ECM-1 have tumor-promoting and tumor-suppressing functions, respectively." (PMID 29858602, 2018). "The inverse correlation between TGFBI and Dkk-3 in cancer was only observed in low Gleason score tumors, suggesting that regulation of TGFBI by Dkk-3 is less important in more advanced prostate cancer." (PMID 29858602, 2018). "Androgen deprivation was found to increase TGFBI levels and TGFBI knockdown suppressed prostate cancer cell migration and inhibited tumor growth and metastasis." (PMID 29858602, 2018). "There was an inverse correlation of TGFBI and Dkk-3 expression in prostate cancer, consistent with the increased levels of TGFBI observed upon DKK3 silencing in RWPE-1 cells." (PMID 29858602, 2018). "For instance, TGFBI was recently proposed as a biologically relevant miR-675-5p target in prostate cancer." (PMID 25889562, 2015). "Up-regulation of miR-675 in the prostate cancer cell line significantly decreased the level of TGFBI and repressed cell migration." (PMID 25889562, 2015). "In this study, we have examined the promoter methylation of the TGFBI gene in 100 cases of lung and prostate cancers by using an optimized MSP method." (PMID 18834524, 2008). "Dense methylation of the TGFBI promoter was present in 38.9% (7/18) of prostate cancer samples with locoregional invasiveness vs. only 19.4% (6/31) of prostate cancer samples without locoregional invasiveness (p < 0.05)." (PMID 18834524, 2008). "We designed methylation-specific primers and optimized MSP conditions to examine the methylation status of the TGFBI promoter in a large number of human lung and prostate cancer specimens." (PMID 18834524, 2008). "In this study, we optimized a methylation-specific polymerase chain reaction (MSP) method and investigated the methylation status of the TGFBI promoter in human lung and prostate cancer specimens." (PMID 18834524, 2008). "Abnormal activation of the TGF-β signaling pathway in benign prostatic epithelium can lead to increased expression of the pro-tumor invasion factor TGFBI, which may contribute to the progression of prostate cancer." (PMID 36035369, 2022). "TGFBI promoter hypermethylation also occurs in lung and prostate cancer specimens." (PMID 33912443, 2021). "H19 is a significantly down-regulated lncRNA in prostate cancer confirmed to inhibit the invasion of tumor cells by targeting TGFBI via regulating miR-675, which could be a biomarker to benefit diagnosis and therapy of advanced prostate cancer." (PMID 35087800, 2021). "Similarly, TGFBI has tumor-promoting and tumor-protective roles in certain gastrointestinal tract cancers, and in prostate cancer." (PMID 32582282, 2020).
prostate carcinoma (continued). "The correlation of ECM-1 and Dkk-3 expression in WPMY-1 cells, ECM-1 inhibition of TGFBI-dependent prostate cancer cell invasion and the correlation of ECM1 and DKK3 expression with relapse-free survival, suggest that ECM-1 also participates in the Dkk-3 defense mechanism." (PMID 29858602, 2018). "TGFBI protein levels were significantly higher in prostate cancer than in benign prostate." (PMID 29858602, 2018). "H19/miR-675 axis inhibits prostate cancer metastasis via affecting TGFBI expression." (PMID 27391349, 2016). "Fifty prostate cancer patient samples were screened for TGFBI methylation by MSP." (PMID 18834524, 2008). "Furthermore, H19/miR-675 repressed prostate cancer metastasis by targeting TGFBI." (PMID 35674441, 2022). "Likewise, in prostate cancer, TGFBI contributes to tumour progression." (PMID 33080107, 2020). "The improvement in RWPE-1 acinar morphogenesis and the inhibition of TGFBI-induced PC3 and C4-2B cell invasion by exogenous ECM-1 suggests that increased expression of ECM-1 in prostate cancer may be beneficial to patients, whereas the opposite may be true for TGFBI." (PMID 29858602, 2018). "Thus, TGFBI promoter hypermethylation may represent a valuable prognostic biomarker in both lung and prostate cancer patients." (PMID 18834524, 2008). "TGFBI is an EMC protein involved in a variety of biological processes such as EMT in tumors, and it has been shown to be an important factor involved in EMT and tumor progression processes in prostate cancer." (PMID 39068456, 2024).
pancreatic cancer (19 papers, 2007 to 2025). "In pancreatic cancer, cancer-associated fibroblasts express high levels of TGFBI which directly acts on tumor-specific CD8+ T cells and F4/80 macrophages in mice, reducing their proliferation and activation." (PMID 36463238, 2022). "This is in contrast to the pancreatic cancer model, where anti-TGFBI treatment increased the number and activation of CD8+ cells." (PMID 34561272, 2021). "We previously reported that inhibiting TGFBI resulted in a remodeling of the pancreatic tumor microenvironment with an enhanced antitumor response." (PMID 34561272, 2021). "The first report to demonstrate that TGFBI acts on tumor immune cells came from studies in pancreatic cancer." (PMID 34561272, 2021). "The HGSOC study reported here, taken together with the findings in pancreatic cancer, would suggest that approaches that target TGFBI are worthy of further investigation." (PMID 34561272, 2021). "We further investigated this and, in accordance with our findings in pancreatic cancer biopsies and mouse pancreatic cancer models, we also identified TGFBI transcript in some of the ACTA2-expressing fibroblasts in the stroma of ovarian and omental metastasis." (PMID 34561272, 2021). "We assessed tumor sections from cholangiocarcinomas, pancreatic carcinomas, hepatocarcinomas and gastric carcinomas for TGFBI expression with immunohistochemistry." (PMID 25889002, 2015). "Based on microarray analysis, TGFBI is among a number of genes up-regulated in human pancreatic carcinomas and human squamous cell carcinomas." (PMID 25889002, 2015). "In pancreatic cancer, TGFBI stimulated the FAK signaling pathway by binding to integrin αVβ5." (PMID 33921897, 2021). "TGFBI was found to be expressed in pancreatic cancer stem cells and is thought to mediate immune tolerance through inhibition of cytotoxic T cell activation in pancreatic cancer." (PMID 28106769, 2017). "The upregulation of the TGF-β-induced TGFBI in BMSCs supports the hypothesis that ColX may originate from “activated,” dysregulated bone marrow-derived mesenchymal cells which infiltrate breast and pancreatic tumors." (PMID 39939916, 2025). "With that said, some patients with pancreatic carcinomas had high serum TGFBI levels, although TGFBI levels as a group were not significantly higher than in the controls." (PMID 25889002, 2015). "TGFBI is known as the primary intracellular downstream signaling mediators of integrins and promotes αvβ5 integrin signaling to FAK (focal adhesion kinase), thereby contributing to cancer progression through its integrin-binding RGD motif in osteosarcoma, colon, and pancreatic cancer models." (PMID 38514830, 2024). "High expression of TGFBI interlinked with poor prognosis in patients has been noted in muscle invasive bladder cancer compared to non-muscle invasive bladder cancer tissues, pancreatic cancer, colorectal cancer, etc." (PMID 36463238, 2022). "If TGFBI is involved in immune suppression and is also found in advanced tumors, we hypothesized that it may contribute to the immune landscape of advanced HGSOC tumors, in line with our previously reported results in a mouse pancreatic cancer model." (PMID 34561272, 2021). "In addition, the interaction of integrin αvβ5 with TGFBI (transforming growth factor beta-induced), an ECM interacting protein that contains RGD motif, promotes the activation of FAK signaling pathway, consequently enhancing glycolysis and invasiveness in pancreatic cancer cells." (PMID 31137693, 2019).
Thiel-Behnke corneal dystrophy (17 papers, 2010 to 2021). Thiel-Behnke corneal dystrophy (TBCD) is a rare form of superficial corneal dystrophy characterized by sub-epithelial honeycomb-shaped corneal opacities in the superficial cornea, and progressive visual impairment. "Reis-Bücklers corneal dystrophy (RBCD; MIM 608470) and Thiel-Behnke corneal dystrophy (TBCD; MIM 602082) are two forms of epithelial-stromal transforming growth factor beta induced (TGFBI) corneal dystrophies." (PMID 27309958, 2016).
lung adenocarcinoma (15 papers, 2007 to 2024). A carcinoma that arises from the lung and is characterized by the presence of malignant glandular epithelial cells. "TGFBI was discovered in the lung adenocarcinoma cell line A549 as a cancer-associated gene induced by TGF-β1." (PMID 31514337, 2019). "Studies showed that TGFBI was induced by TGF-β in the lung adenocarcinoma cell line and overexpression of TGFBI was associated with some malignancies, such as RCC and hemangioblastoma." (PMID 22950635, 2012). "TGFBI (transforming growth factor β-induced protein), encoded by TGFBI gene, was first identified in a human lung adenocarcinoma cell line A549 treated with TGFB (transforming growth factor β), it contains an RGD (Arg-Gly-Asp) motif that can serve as a ligand recognition site for integrins." (PMID 33912443, 2021). "TGFBI, also called Betaig-h3, was first identified during the 1990s, when it was isolated from a human lung adenocarcinoma cell line (A549) which had been treated with TGF-β." (PMID 22695319, 2012). "TGFBI, also known as βig-H3, is a gene cloned from TGFβ-stimulated A549 lung adenocarcinoma cells." (PMID 36841925, 2023). "TGFBI, also known as βig-H3, is a gene cloned from TGFβ1-stimulated A549 lung adenocarcinoma cells." (PMID 25889002, 2015). "TGFBI, the transforming growth factor-beta induced gene (also known as BIGH3, OMIM 601692), was initially observed to be inducibly expressed in the human lung adenocarcinoma cell line A549 and in several other cell lines in 1992." (PMID 22194646, 2011).
melanoma (15 papers, 2009 to 2026). A malignant, usually aggressive tumor composed of atypical, neoplastic melanocytes. "Melanoma had the highest frequent TGFBI alteration (>6%), with “mutation” as the primary type of alteration." (PMID 34671645, 2021). "TGFBI is a secreted extracellular matrix protein that has been shown to be important for the growth of melanoma distal metastases after intravenous injection in a mouse model but not for initial dissemination or extravasation to the metastatic site." (PMID 40717170, 2025). "Among the genes directly modulated by PHF8, we found TGFβ-induced (TGFBI), a secreted extracellular matrix component that confers high metastatic potential to melanoma cells." (PMID 35179962, 2022). "In melanoma cells, TGFBI plays an anti‐adhesive role and its knockdown decreases tumour growth and invasion." (PMID 33080107, 2020). "TGFBI silencing effectively reduces cell proliferation and elevates motility of melanoma cells in vitro." (PMID 30379886, 2018). "Interestingly, several of these AhR‐associated genes have been involved in the aggressiveness of melanoma or other cancers and have been associated with a poor prognosis (ABCG2, COL1A1, COL6A1, COL6A2, TGFBI)." (PMID 36305167, 2022). "The findings that siRNA TGFBI knockdown increased melanoma cell growth and invasion in vitro but greatly impaired subcutaneous tumor growth in nude mice highlights the importance of the tumor microenvironment for βig-H3 function." (PMID 22949874, 2012). "Whole genome expression analysis uncovered two reactivated TGFβ-responsive genes Clusterin and TGFBI that were more prominent in Aza-sensitive compared to resistant melanoma cells, and their activation enhanced apoptosis as observed by siRNA mediated gene knockdown." (PMID 19234609, 2009). "Furthermore, WAY-316606 markedly impaired the migratory and invasive capacities of metastatic melanoma cells, accompanied by downregulation of key ECM remodeling and fibrosis-related genes, including VIM, CCN2, FN1, and TGFBI." (PMID 42279305, 2026). "Furthermore, TGFBI promoter methylation might be useful as a marker for malignant transformation because it was unmethylated in normal melanocytes and hypo- or fully methylated in freshly isolated primary and metastatic melanoma cells, as well as melanoma tumors." (PMID 19234609, 2009). "Furthermore, known melanoma markers, such as MCAM, TNC, and TGFBI, were upregulated in melanoma EVs but not in depleted melanoma plasma, highlighting the specific information contained in EVs." (PMID 38353833, 2024). "TGFBI promoter methylation was not restricted to metastatic cells or to cells in culture, because it was also methylated in primary melanoma cells freshly isolated from a 2.2 mm lesion (passage 1) and in five independent snap-frozen metastatic tumors (data not shown)." (PMID 19234609, 2009). "Among the upregulated candidates in plasma-derived EVs were melanoma markers, such as MCAM, TNC, and TGFBI, which were not regulated in depleted plasma samples." (PMID 38353833, 2024). "Sequencing of BS modified DNA revealed that TGFBI promoter was unmethylated and partially methylated in expressing normal human melanocytes and YUSIT1 melanoma cells, and completely methylated in non-expressing melanoma cells WW165, YUGEN8, YUMAC and YUSAC2." (PMID 19234609, 2009).
glioblastoma (14 papers, 2010 to 2025). The most malignant astrocytic tumor (WHO grade IV). "In contrast to a study performed in a glioblastoma cell line, overall expression and secretion of TGFBI was unaffected by either loss or gain of SPARC in the Met5a cell line." (PMID 27622658, 2016). "In our previous study, we elucidated the significant role of transforming growth factor beta-induced protein (TGFBI), a protein secreted by M2-like tumor-associated macrophages, in promoting the malignant behavior of glioblastoma (GBM) under normoxic conditions." (PMID 39346536, 2024). "TGFBI is expressed at higher levels in mesenchymal glioblastoma tumors and is reported as a potential signature gene for the mesenchymal subtype." (PMID 35454889, 2022). "For example, TGFBI is highly expressed in glioblastoma multiforme (GBM) and is related to DC cell infiltration, which is an adverse biomarker of GBM." (PMID 34671645, 2021). "Another relevant example is TGFBI which, besides its recognized role as a marker of the mesenchymal class of glioblastoma, was described, in conjunction with SOX4, as a mediator of non-SMAD mediated TGF-beta signaling pathways in glioblastoma." (PMID 26188123, 2015). "Moreover, TAM-derived TGFBI promotes glioblastoma growth through integrin αvβ5-Src-Stat3 signaling." (PMID 38297161, 2024). "TGFBI significantly influences tumor progression and dissemination in NSCLC and is markedly overexpressed in various cancers, notably glioblastoma multiforme (GBM), where it is associated with poorer patient outcomes and increased chemotherapy resistance." (PMID 40510341, 2025). "We identified the following five proteins that were present in all samples, both glioblastoma-derived EVs and HPA-derived EVs: THBS1, FN1, TGFBI, ACTN4, and LGALS3BP." (PMID 35454889, 2022).
lattice corneal dystrophy type I (14 papers, 2008 to 2026). Type I lattice corneal dystrophy (LCDI) is a frequent form of stromal corneal dystrophy characterized by a network of delicate interdigitating branching filamentous opacities within the cornea with progressive visual impairment and no systemic manifestations. "Within this pedigree, RBCD segregates with the R124C variance, which is a known mutation for lattice corneal dystrophy type I. Therefore, along with G623D and R124L, the R124C mutation in TGFBI is also found to be responsible for RBCD." (PMID 20360992, 2010). "We report for the first time the presence of the TGFBI mutation segregating with lattice corneal dystrophy type I in Chilean patients." (PMID 18470323, 2008). "Here, we demonstrated an unusual R124C mutation in TGFBI associated with the RBCD, which was a mutation known to be responsible for corneal lattice dystrophy type I. Therefore, along with G623D and R124L, the R124C mutation in TGFBI is also found to be responsible for RBCD." (PMID 20360992, 2010). "Genomic DNA was extracted from peripheral leukocytes from six affected and three unaffected members of a family with lattice corneal dystrophy type I. Exon 4 of the transforming growth factor-induced gene (TGFBI) was screened for the most frequent mutation, R124C, in the proband by sequencing." (PMID 18470323, 2008). "Lattice corneal dystrophy Type I (LCD-1), a rare inherited disorder caused by mutations of TGFBI, manifests with amyloid deposition within the corneal stroma and causes visual impairment." (PMID 41726249, 2026). "Furthermore, identification of the p.Leu509Arg in a French family with lattice-type corneal dystrophy raises the need to reconsider the role of TGFBI in the molecular diagnosis of Epithelial basement membrane dystrophy (EBMD)." (PMID 21617751, 2011).
Reis-Bücklers corneal dystrophy (13 papers, 2008 to 2025). "LCD type IIIA caused by the P501T mutation of TGFBI and atypical granular corneal dystrophy caused by the D123H mutation of TGFBI are thought to have a low penetrance." (PMID 19461933, 2009). "Mutations in the transforming growth factor-beta-induced (TGFBI) gene are responsible for granular, lattice and Reis-Buckler corneal dystrophy, and each dystrophy developed characteristic corneal opacities that cause visual disturbance." (PMID 26197481, 2015).